Y_RNA (Y RNA )
Gene: Miscellaneous RNA gene on chromosome 18 (32,263,135 to 32,263,234, reverse strand). Ensembl gene ENSG00000222395.
Homologues: Orthologues: chimpanzee Y_RNA (99% identical). Paralogues in human: Y_RNA (81% identical), Y_RNA (80% identical), Y_RNA (79% identical), Y_RNA (78% identical), Y_RNA (77% identical), RNY1 (76% identical), RNY1P16 (76% identical), Y_RNA (76% identical), RNY1P5 (75% identical), Y_RNA (75% identical), Y_RNA (74% identical), Y_RNA (73% identical), and 91 more.